ERBB2 (erb-b2 receptor tyrosine kinase 2)
Diseases named in the same sentence as ERBB2 in open-access papers (continued):
Sharing a sentence is not in itself a finding about the gene and the disease.
cancer (continued). "In particular, ganetespib, a novel HSP90 inhibitor, is a promising agent for ErbB2+ cancers." (PMID 29717218, 2018). "Moreover, combining inhibitors of ERBB2 and chromatin readers to prevent kinome reprogramming blocked outgrowth of adapted cancer cells assessed with in vitro assays." (PMID 29458371, 2018). "Interestingly, they found a pro-oncogenic gene expression signature in early neoplasia which was distinct from normal tissues and carcinoma (DCIS/IDC) including up-regulation of ERBB2, FOXA1, and GATA3." (PMID 29720211, 2018). "ErbB2 is involved in many physiological and pathological processes, such as cancer." (PMID 28306722, 2017). "ErbB2 therefore carries an exponentially aggravated oncogenic and transforming potential and represents an excellent molecular candidate for selective anti-cancer targeted therapy." (PMID 29143776, 2017). "Here we investigated whether H2-18 could also overcome acquired resistance to trastuzumab in ErbB2-amplified cancers." (PMID 28514745, 2017). "In conclusion, H2-18 may have the potential as an effective agent to circumvent acquired resistance to trastuzumab in ErbB2-overexpressing cancers." (PMID 28514745, 2017). "Taken together, these data suggest that epigenetic regulation might be a possible mechanism of miR-23b downmodulation in p130Cas/ErbB2 cancer cells." (PMID 28442738, 2017). "Since miR-3622b-5p induces the apoptosis of ERBB2-positive cancer cells, it is proposed that miR-3622b-5p might evoke the apoptosis of ERBB2-positive cancer cells by weakening drug resistance." (PMID 28160563, 2017). "These TCGA data analyses may support the hypothesis that the co-amplified genes identified as potential CPGs for GC in this study play pro-oncogenic roles in other cancers as well, similar to ERBB2 and MET." (PMID 29190909, 2017). "CAR-T for ERBB2 cancer cell targeting may be used to complement other treatment modalities such as immune checkpoint inhibitors, oncolytic virus, and nanoparticles, or even with other types of immune effector cells, such as natural killer cells." (PMID 28885562, 2017). "Our findings may also help in understanding the consequences of dysregulated ErbB2 signaling in other cancer types where ErbB2 overexpression occurs in a significant proportion of cases." (PMID 28174229, 2017). "In conclusion, H2-18 may have the potential to circumvent trastuzumab resistance in ErbB2-amplified cancers." (PMID 28514745, 2017). "ER+/HER2− cancer cells, instead, sense the microenvironment activating inflammatory and metabolic pathways, and the resulting transcriptional changes, when detected in clinical tumors, are associated with a grim prognosis for women with ESRI+/ERBB2− tumors." (PMID 28672102, 2017). "For example, the luminal B subtype cancers are treated with endocrine therapies in combination with ERBB2 targeted drugs, because the crosstalk between ER and ERBB2 can lead to endocrine therapy resistance, while ERBB2-positive subtype tumors can benefit from ERBB2 targeted drugs." (PMID 28415602, 2017). "Particularly, EGFR and ErbB2 proteins hyperactivate theses pathways in a broad range of cancers." (PMID 28417948, 2017). "Nearly 2% of all cancers harbor hotspot or putative activating mutations in ERBB2, suggesting that these cancers may be sensitive to HER2-targeted therapies." (PMID 29371993, 2017). "Both EGFR and ErbB2 play an important role in regulating cancer stemness." (PMID 29156633, 2017).
cancer (continued). "In cancer cells, Necl-4 is down-regulated or dysfunctional and its inhibitory effect on the ligand-induced dimerization of ErbB3 with ErbB2 may be abolished." (PMID 28900130, 2017). "Therefore, there is a continuing need for the development of additional therapies against ErbB2‐enriched cancer." (PMID 28781955, 2017). "Immunohistochemistry and FISH demonstrated that most cancer cells containing such mutations were not overexpressing the ErbB2 protein." (PMID 28417948, 2017). "Our data demonstrate the cooperation between CA and Tz in inhibiting cell migration and survival of ERBB2+ BC cells that warrant further studies to establish if CA or CA derivatives may be useful in vivo in the treatment of ERBB2+ cancers." (PMID 29100552, 2017). "The overexpression of ErbB2 protein in cancer cells made from this member of the family one of the preferred partners for heterodimerization; if there are not enough ErbB family partners on the surface of the cells, ErbB2 can form spontaneously homodimers." (PMID 28286519, 2017). "High levels of ErbB2 in cancer cells induce ligand-independent constitutive dimerization of ErbB2 and/or dimerization with other epidermal growth factor receptor family members, triggering downstream signaling through the phosphoinositide-3-kinase (PI3K)–AKT and Ras–Raf–MEK–ERK1/2 cascades." (PMID 27791982, 2017). "We observed that Mek inhibition does not alter ErbB2 mRNA levels in detached cancer cells and that ErbB2 protein loss induced by this inhibition can be blocked by a lysosomal inhibitor." (PMID 29285258, 2017). "Over-expression or amplification of ERBB2 is observed in multifarious carcinomas." (PMID 28160563, 2017). "Therefore, characterization of other phosphorylation sites and their physiological functions is essential for full understanding of the activation and inactivation mechanisms for ErbB2 in cancer cells." (PMID 27531070, 2016). "Thus, for some, most, or all ErbB2-positive cancers, ErbB2 itself continues to represent a major vulnerability." (PMID 27564098, 2016). "ErbB1 and ErbB2 are members of the ErbB family of cell surface receptor tyrosine kinases, which also include ErbB3 and ErbB4, and are important therapeutic targets in many forms of cancer." (PMID 27286447, 2016). "Therefore, distinct and complementary effects of FCF, and geldanamycin present a potential for augmented targeting of ErbB2 persistence in cancer." (PMID 28066764, 2016). "A panel of 18 HER2+ (ERBB2-amplified) cell lines representing a variety of indications was used to characterize the functional and molecular diversity within this oncogene-defined cancer." (PMID 27035903, 2016). "In many different cancer cells, ErbB2 is amplified by increased gene transcription." (PMID 27596216, 2016). "The ERBB2 pathway is overexpressed in several cancers and contributes to cell growth and survival." (PMID 27203740, 2016). "The breast is the most well-studied context for the role of ELF5 in cancer, with microarrays showing increased expression in basal-like subtypes and decreased expression in luminal A/B and Erb-b2 receptor tyrosine kinase 2 (HER2)-overexpressing subtypes, suggesting subtype-specific effects." (PMID 26738740, 2016). "Here, we explore how spatial in-homogeneities in the plasma membrane might influence the dimerization and phosphorylation status of ErbB2 and ErbB3, two receptor tyrosine kinases that preferentially heterodimerize and are often co-expressed in cancer." (PMID 27570763, 2016). "Thus, further research should be performed in order to fully understand the impact of nucleolin-mediated ErbB2 signaling, and its possible implications on cancer therapy of ErbB2-positive cancers." (PMID 27542246, 2016). "Little attention has been paid to the role of ErbB2 degradation in cancers, although when compromised, it may lead to increased ErbB2 levels and activity." (PMID 26716506, 2016).
cancer (continued). "Therefore, we have concluded that, indeed, ErbB2 directly binds nucleolin, and that this interaction occurs endogenously in normal and cancer cells." (PMID 27542246, 2016). "Thus, understanding ErbB2-mediated signaling is crucial for further development of anti-cancer therapeutics and disease treatment." (PMID 27542246, 2016). "ErbB-2 is a target for cancer-initiating cells in breast and other cancers." (PMID 26044366, 2015). "ErbB2 is commonly overexpressed and frequently amplified in cancers, including PDAC." (PMID 25890497, 2015). "It has recently been suggested that the gain of ERBB2 in normal cells in the vicinity but outside the focus of primary tumor might represent an event related to infiltration of cancer cells into the normal parenchyma." (PMID 26430163, 2015). "As mir-4728 decreases the activity of ERK, a key downstream effector of ErbB2 signaling, mir-4728 may have potential in the treatment of ErbB2-overexpressing cancers, when delivery of miRNAs becomes a viable therapeutic option." (PMID 25950472, 2015). "Moreover, in cancer cells, CDK5, ERBB2/ERBB3, and beta-catenin have been linked through another member of the beta-catenin network—the androgen receptor (AR)." (PMID 26509276, 2015). "Thus, we examined the sensitivity of DF in combination with the EGFR/ERBB2-targeting reagent lapatinib on cancer cells." (PMID 24587811, 2014). "In addition to known cancer driver genes such as ERBB2 (6% of cases), NRAS (3%), MET (3%), PIK3CA (1%), AKT2 (1%), TSC1 (1%), and ERBB4 (1%), several putative cancer genes were identified, such as PTPRC, SYNE2, GRIN2A, and CDH10." (PMID 24576404, 2014). "Since GRB7 is a molecular adaptor for EGFR receptor tyrosine kinases, including ERBB2, the amplification of GRB7 may have a functional consequence in Her-2 driven cancers." (PMID 24874471, 2014). "ErbB2 signaling plays a key role in development and in certain diseases, such as cancer." (PMID 24824849, 2014). "ERBB2 encoding the protein HER2 (human epidermal growth factor receptor 2) is a member of the epidermal growth factor receptor (EGFR) family, and it has been shown to play an important role in the pathogenesis and progression of many different types of cancer." (PMID 25106096, 2014). "ErbB-2 phosphorylation and RhoA activation are required for several downstream cellular effects including the promigratory and prometastatic effects of semaphorins on cancer cells and Sema4D-induced axonal growth cone collapse." (PMID 25137062, 2014). "Moreover, biotin-conjugated EC1 and the recombinant protein, EC1-eGFP, retained the affinity for ErbB2, and were selectively internalized into ErbB2-overexpressing cancer cells." (PMID 25190023, 2014). "Cancer-specific ERBB2 and MAPK signaling pathways are downloaded from KEGG database." (PMID 25034693, 2014). "However, addition of the A5/F4 oligoclonal to cetuximab treatment enhanced the extent and time of pAKT inhibition, similar to what was seen with the A5/F4 plus trastuzumab in ERBB2-driven cancer cells." (PMID 25386657, 2014). "In addition to full length ErbB2, truncated forms of ErbB2, collectively referred to as p95HER2, exist in a subgroup of ErbB2 positive cancers." (PMID 25102001, 2014). "Recent reports suggest that ERBB2/GRB7 co-amplification may be a necessary step for cancer progression in specific cancer types, such as Barrett's carcinoma." (PMID 24874471, 2014). "Genetic modifications in other genes, including targeted mutations in BRAF, AKT1, ERBB2 and PIK3CA, as well as ROS1- and RET-involved fusions, may also affect cancer therapy." (PMID 24646369, 2014). "How does ErbB2 activation make cancer cells invasive and when?" (PMID 24709902, 2014).
cancer (continued). "The invasive activity of cancer cells overexpressing ErbB-2 is mediated by Plexin-B1 and RhoA." (PMID 25137062, 2014). "Trastuzumab has shown significant efficacy in human cancer patients with ErbB2 overexpression." (PMID 24824849, 2014). "Furthermore, binding assays on ERBB2-positive human cancer cells demonstrated that the ADAPTs specifically recognized the native receptor." (PMID 25089830, 2014). "Therefore, a better understanding of the entire array of downstream changes should allow the identification of novel actionable targets and the development of more effective and durable strategies for the treatment of ErbB2-positive cancers." (PMID 25238247, 2014). "ERBB2 is necessary for induction of carcinoma cell invasion 14, so we speculated that pri-miR-125a mutant genotype may enhance cell invasive capacity via increasing the expression of ERBB2." (PMID 25479352, 2014). "Moreover, in carcinoma tissues, IL-33 expression is significantly higher in HER2-overexpressing tissues, consistent with the report that its receptor sST2 is over-expressed to promote BC metastases upon ErbB2 activation in BC cell lines." (PMID 24778632, 2014). "Thus, the present study demonstrates EC1-GLuc-p53C to be an effective theranostic reagent targeting ErbB2 for bioluminescence imaging and cancer therapy." (PMID 24069396, 2013). "The overexpression of ErbB genes, particularly ErbB2, has been observed in human cancer." (PMID 23739740, 2013). "In conclusion, EC1-GLuc-p53C may be a promising theranostic reagent for ErbB2-overexpressing cancer in vitro and in vivo." (PMID 24069396, 2013). "The ErbB2/HER2 transmembrane tyrosine kinase is overexpressed in a number of human cancers." (PMID 23300147, 2013). "In addition, EC1-fused molecules are selectively internalized into ErbB2-overexpressing cancer cells." (PMID 24069396, 2013). "A number of researches demonstrated that overexpressions of EGFR and ErbB-2 has been observed in many cancer patients and correlate with a poor prognosis for several tumors including non-small-cell lung cancer (NSCLC), prostate, breast, stomach, colon, and ovarian cancers." (PMID 23936329, 2013). "Moreover, biotin-conjugated EC1 and the recombinant protein EC1-eGFP retained affinity for ErbB2 and were internalized by ErbB2-overexpressing cancer cells." (PMID 24069396, 2013). "Trastuzumab can also be conjugated to DM1, an inhibitor of tubulin polymerization derived from maytansine, to efficiently deliver DM1 to ERBB2-overexpressing cancer cells." (PMID 23630663, 2013). "ErbB2 overexpression is weakly predictive of cancer mortality." (PMID 22991510, 2012). "In addition, the cancer cells were marked with high ErbB2 which indicated strong proliferation of epithelial cancer cells." (PMID 23133563, 2012). "The over-expression of ErbB2 in the context of cancer might then bring about the aberrant recruitment of many SH2-containing proteins, thus eliciting increased mitogenesis, migration, and survival." (PMID 22973453, 2012). "ErbB2 is commonly overexpressed in cancers, including PDAC, where ErbB2 is frequently amplified." (PMID 22393391, 2012). "Thus, a fairly common mechanism in cancer is the up-regulation of expression of members of the epidermal growth factor receptor family such as EGF receptor or Her2/ErbB2." (PMID 23905066, 2012). "Thus, a better understanding of the changes in cell polarity proteins in ErbB2 positive cancers can identify novel ways to treat and/or predict cancer progression." (PMID 22529912, 2012). "A stronger significance level was also achieved on Cox regression analysis compared with when only ERBB2 was used, which may reflect the multigenic nature of cancer." (PMID 22938721, 2012). "Moreover, it has previously been reported that integrin-β1 binds to ErbB2 in human carcinoma cell lines." (PMID 22817771, 2012). "Therefore, it is conceivable that the ErbB2/ErbB3 pathway can contribute to formation of malignant tumors." (PMID 22216327, 2011).
cancer (continued). "In conclusion, erbB2 and NFκB overexpression are relevant to CRT resistance of MIBC, and overexpression of at least one of these oncoproteins potentially increases the risk for cancer death in MIBC patients treated with induction CRT and cystectomy." (PMID 22102915, 2011). "Furthermore, also carcinomas with a high expression of ErbB2, such as non-small cell lung carcinoma, gastric and prostatic tumours, have been found to be resistant or much less sensitive to Trastuzumab treatment." (PMID 21559015, 2011). "Spontaneous induction of ErbB2-specific helper and cytotoxic T-cells and serum antibodies in patients with ErbB2+ carcinomas suggest that these may be possible." (PMID 24212954, 2011). "Preclinical trials on cohorts of wild-type mice challenged with transplantable syngeneic ErbB2+ tumors or mice engineered to develop a specific ErbB2+ carcinomas are used to assess the protective potential of a vaccine and tease apart the mechanisms on which it depends." (PMID 24212954, 2011). "This study showed that the cancers could be classified into a basal epithelial-like group, an ERBB2-overexpressing group, and a normal breast-like group." (PMID 20487548, 2010). "CSAGAs and their association with human cancers in the regions outside of the ERBB2 amplicon core region in 17q12 have not been studied." (PMID 20158880, 2010). "HER2/ErbB2 amplification is a frequent and well-studied event in breast and other cancers." (PMID 20628393, 2010). "Both immunoagents are selectively cytotoxic for ErbB2-positive cancer cells in vitro and in vivo." (PMID 20051960, 2010). "The 'ERBB2' signature, although present in cluster 1, nevertheless shows strong correlation with other prognostic signatures, as expected for the important role of ERBB2 over-expression in cancer prognosis." (PMID 19327144, 2009). "Therapeutic treatments targeting the eIF2α pathway may prove, alone or in combination with other targeted therapies, to be useful in the treatment of cancers over-expressing ErbB2." (PMID 19754954, 2009). "Signaling through EGFR (ErbB1) and its family members ErbB2 (Her2/Neu2) ErbB3 and ErbB4 regulates cellular processes such as survival, proliferation, differentiation and motility and ErbB receptors are important targets for new and existing anti-cancer drugs." (PMID 19662154, 2009). "Together these findings suggest that ErbB2 positive cancer cells in lesions like DCIS might be particularly sensitive to therapeutic drugs that enhance eIF2α phosphorylation." (PMID 19754954, 2009). "Although no physiological E3 ligases for the estrogen receptor (ESR1) and ERBB2 ubiquitylation have yet been identified, this model could prove useful for understanding ERBB2-positive cancer." (PMID 19007432, 2008). "Elevated Stat3 phosphorylation in these bladder tissues and cell lines might result from abnormal overactive upstream oncogenic FGFR or ERBB2 in these cancer tissues." (PMID 18939995, 2008). "Understanding the mechanisms that protect ERBB2-overexpressing cancer cells from apoptosis might result in new targets for therapeutic intervention." (PMID 19007432, 2008). "Immunohistochemistry may help, as more than 90% of SDCs are specifically positive for androgen receptors (AR) and because most of these carcinomas show positive staining for HER-2/neu (c-erbB-2)." (PMID 18667060, 2008). "Similarly, in 1M-84, DHFR* is integrated between PCGF2 (Mel-18) and PSMB3, approximately 1 Mb proximal to ERBB2, a gene frequently amplified in cancer." (PMID 17584934, 2007). "Since true classes are usually not known a priori for novel cancer subtypes, we focused our attention on a subtype where gene expression profiles associated with an independent immunohistochemical marker: Her-2 / erbB2 status." (PMID 15850491, 2005). "In addition, one of the first approved targeted cancer therapeutics was Herceptin, an antibody inhibitor of ErbB2." (PMID 15305194, 2004).